TBK1 (TANK binding kinase 1)
Diseases named in the same sentence as TBK1 in open-access papers (continued):
Sharing a sentence is not in itself a finding about the gene and the disease.
COVID-19 (21 papers, 2020 to 2026). A disease caused by infection with severe acute respiratory syndrome coronavirus 2. "In the same work, patients harboring TICAM1 or TBK1 deficiency were tested to evaluate IFN-α levels during the acute phase of COVID-19." (PMID 35062298, 2022). "A CVID patient with NF-kB2 loss-of-function variant who developed severe COVID-19 and a patient with TBK1 and TNFRSF13B mutations and an auto-inflammatory disease with lethal COVID-19 were reported." (PMID 35126372, 2021). "In our opinion, however, the currently available evidence favors the TBK1 variant over the other two factors as a driver of the severe COVID-19 disease course." (PMID 34210994, 2021). "At the crossroads of autophagy and interferon production pathways, our results highlight that TBK1 is a pivotal gene whose mutations may have deleterious effects in both viral-induced diseases, such as COVID-19, and sarcoidosis." (PMID 34440765, 2021). "There was increased transcription of TBK1 and a reduction in transcription of TNFα by RT-qPCR in the COVID-19 group." (PMID 40649826, 2025). "The analysis of gene expression associated with viral recognition by host cells, antiviral and pro-inflammatory markers revealed that the COVID-19 group showed an increased expression of TBK1 transcripts compared to the healthy control group." (PMID 40649826, 2025). "In particular, autosomal-recessive deficiencies in IRF7 and IFNAR1 and autosomal-dominant deficiencies in TLR3, TBK1, IRF3, IRF7, IFNAR1 and IFNAR2 genes have been found in a small percentage of patients with severe influenza and COVID-19." (PMID 35846766, 2022). "Of these, one homozygous variant in the genes TBK1 and TNFRSF13B, respectively were considered likely causal factors for the severe COVID-19 disease course observed in the present case." (PMID 34210994, 2021). "Interestingly, recent studies on host genetic susceptibility to severe forms of COVID-19 have shown that germline mutations of TBK1 could be a predisposing factor to SARS-CoV2-induced acute respiratory distress syndrome and severe and/or fatal prognosis of infected patients." (PMID 34440765, 2021). "Overall, a plausible hypothesis is that the present TBK1 variant caused an untuned IFN type I response, which led in turn to a propensity to a severe COVID-19 disease course." (PMID 34210994, 2021). "It has been found that about 3.5% of COVID-19 patients had known autosomal-recessive (AR) deficiencies [interferon regulatory factor 7 (IRF7) and IFNAR1] and autosomal-dominant deficiencies (AD) [toll-like receptor 3 (TLR3), UNC93B1, TICAM1, TBK1, IRF3, IRF7, IFNAR1, and IFNAR2]." (PMID 34335535, 2021). "A bioinformatics analysis of the single-cell and bulk RNA-seq profiling of COVID-19 patients’ data revealed a significant upregulation of cGAS-STING signalling pathway genes (TMEM173, IRF3, NFKB1, CGAS, IFNAR1, and TBK1) in the lung." (PMID 39459875, 2024). "In this sense, IFN polymorphisms or polymorphisms of the molecules in charge of signaling for their production, such as IRF3, IRF7, TICAM1, TBK1, and STAT2, have also been related to poor prognosis of COVID-19 patients." (PMID 35062298, 2022). "The N protein of SARS-CoV-2, the etiological agent of COVID-19, also has been shown to inhibit IFN induced by SeV, poly(I:C), RIG-I, MAVS, TBK1, and IKKε." (PMID 34220846, 2021).
pancreatic cancer (17 papers, 2014 to 2025). "Both TBK1 and IKKε have been linked with pancreatic cancer cell phenotypes." (PMID 40738190, 2025). "In particular, TBK1 activation has been linked to skin and pancreatic cancer development." (PMID 38816352, 2024). "This suggests that IKKε and TBK1, together, promote an environment for cancer stem cell formation and maintenance in pancreatic cancer cells, thereby contributing to aggressiveness." (PMID 40738190, 2025). "To further explore oncogenic roles of KRAS and MAPK signaling, as well as investigate potential overlapping and distinct cancer-related roles of TBK1 and IKKε, we studied their expression in pancreatic cancer." (PMID 40738190, 2025). "Long-term studies are needed to identify potential substrates for TBK1 and/or IKKε that contribute to their phenotypic effects in pancreatic cancer cells." (PMID 40738190, 2025). "Previously, others have studied the effects of the related kinases TANK-binding kinase 1 (TBK1) and inhibitor of nuclear factor kappa-B kinase epsilon (IKKε) in pancreatic cancer where they have been shown to promote cell survival." (PMID 40738190, 2025). "The data suggest the importance of regulation of IKKε by ERK in pancreatic cancer cells and of the combined oncogenic activity of TBK1 and IKKε." (PMID 40738190, 2025). "To study the effects of TBK1 and IKKε on pancreatic cancer cell growth, we plated MIA PaCa-2 cells at a low seeding density on 6-well cell culture plates before treatment with siRNA targeting TBK1, IKKε, or both kinases (siDual)." (PMID 40738190, 2025). "To explore this relationship further, we profiled expression of TBK1 and IKKε in pancreatic tumor–adjacent tissues relative to patient-derived pancreatic xenograft tumor samples." (PMID 40738190, 2025). "The non-receptor tyrosine kinase Axl was reported to be a TBK1 activator and regulate TBK1-driven epithelial cell plasticity in pancreatic cancer." (PMID 39279883, 2024). "It was reported that the overexpression of BACH1 induced by tank binding kinase 1 (TBK1) increases intracellular labile iron and decreases the expression of E-cadherin (encoded by CDH1), thereby promoting the metastasis of pancreatic cancer cells." (PMID 38321558, 2024). "TBK1 has been demonstrated to contribute to tumorigenicity in human pancreatic cancer by promoting cell growth, migration, and invasion." (PMID 36928362, 2023). "We analyzed the mRNA expression data from TCGA using the GEPIA database (Gene Expression Profiling Interactive Analysis) and found that the expression of BACH1 and TBK1 are positively correlated in pancreatic cancer." (PMID 36009179, 2022). "The disappointing results in this study do not support further development of MMB as a component of first-line therapy in pancreatic cancer, but TBK1 remains a significant target of interest." (PMID 30105668, 2019). "In support of the contribution of TBK1 to RAS-induced EMT, we reported that TBK1 expression is associated with a poor prognosis in pancreatic cancer patients." (PMID 31681587, 2019). "Next, we knocked down STING expression in pancreatic cancer organoids and added the TBK1 inhibitor MRT67037 to confirm whether D166 exerts its tumor-killing effects through the cGAS-STING pathway." (PMID 40520004, 2025). "Furthermore, ATM inhibition was reported to activate TBK1 in a cGAS-STING-independent manner via SRC kinase in pancreatic cancer cells." (PMID 38084916, 2024). "Ras-RalB-mediated TBK1 activation extends to pancreatic cancer." (PMID 39279883, 2024). "Consistent with this hypothesis, it has been reported that TBK1 enhances the invasive and metastatic capacity of pancreatic cancer cells." (PMID 36009179, 2022). "In the KRasLSL-G12D/+Cdkn2aLox/LoxPtf1aCre/+ PDA mouse model, Tbk1 deletion in the malignant cells resulted in reduced tumor load and reduced metastatic behavior, indicating that Tbk1 activity contributes directly to the aggressive properties of pancreatic cancers." (PMID 35395857, 2022).
pancreatic cancer (continued). "Furthermore, we found that the loss of TBK1 function resulted in reduced invasion, migration, and tumor growth, and reduced metastatic events in preclinical models of mutant KRAS PDAC, indicating that TBK1 actively contributes to pancreatic cancer progression." (PMID 31681587, 2019). "We reported recently that TBK1 maintains the amounts of BACH1 mRNA and protein in pancreatic cancer cells." (PMID 38673728, 2024). "AXL induced TANK binding kinase 1 (TBK1)-NF-κB signaling pathway and innate immune suppression in the TME in pancreatic cancer, while inhibition of AXL with small molecule R428 enhanced immune stimulatory microenvironment." (PMID 37469409, 2023). "Finally, we aimed to determine if the effect on IKKε, and possibly TBK1, would be seen in KRAS-mutant, non-pancreatic cancer cells." (PMID 40738190, 2025). "Individual knockdown of either IKKε or TBK1 did not confer a significant growth defect in KRAS mutant MIA PaCa-2 pancreatic cancer cells, however, double knockdown reduced cell growth and induced cell death." (PMID 40738190, 2025). "Knockdown of IKKε and TBK1 individually does not affect growth of MIA PaCa-2 pancreatic cancer cells, but dual knockdown significantly inhibits MIA PaCa-2 growth, which is mediated through cell death." (PMID 40738190, 2025). "As no OS or PFS benefit vs nab-P + G was apparent in context of suboptimal engagement of the target TBK1, this study does not support further development of MMB as a first-line therapy in pancreatic cancer." (PMID 30105668, 2019).
systemic lupus erythematosus (15 papers, 2012 to 2025). An autoimmune multi-organ disease typically associated with vasculopathy and autoantibody production. "Limiting pathogenic IFN-Is production through TBK1 inhibition may alleviate lupus." (PMID 29559975, 2018). "Inhibitors of NIK, IKKα, and TBK1 represent promising candidates for modulating this pathway and restoring immune homeostasis in lupus." (PMID 40672954, 2025). "Recent studies have shown that blocking STING/TBK1 signaling plays a central role in many diseases such as lung adenocarcinoma, chronic pain and lupus." (PMID 37081450, 2023). "TREX1-deficient mice develop aberrant interferogenic responses and features of lupus owing to the cytoplasmic accumulation of endogenous nucleic acids and chronic activation of the TBK1-dependent DNA-sensing pathway." (PMID 29559975, 2018). "We examined the protein levels as well as upstream kinase activities of IκB including IKKα, β, ε and TBK1 in normal and B cells from lupus patients as well as tonsil B cells which were stimulated with recombinant CD154." (PMID 22952582, 2012). "TBK1 inhibitors are being explored for their roles in treating inflammatory diseases and cancer and may also serve as a therapeutic target for lupus." (PMID 40672954, 2025). "A more attractive candidate is IFN induced protein with tetratricopeptide repeats 3 (IFIT3), which is highly up-regulated in SARS-CoV-2 infected bronchial epithelial cells: IFIT3 interacts with both STING and TANK-binding kinase 1 genes, and activate them in some disorders like lupus." (PMID 33335532, 2020). "Mutations leading to aberrant activation of TBK1 and IFN-Is overproduction can contribute to lupus." (PMID 29559975, 2018). "Overactive TBK1 can precipitate IFN-Is and lupus, such as is the case for TREX1 deficiency." (PMID 29559975, 2018). "For example, in systemic lupus erythematosus (SLE), TBK1 expression in patient immune cells increases with disease activity, particularly in CD4+ T cells and myeloid cells." (PMID 40076567, 2025). "The importance of interferons was highlighted in our previous results on the TLR4 signaling pathway, where TLR4, TICAM1, TICAM2, TBK1, IRF3, IFNA1, and IFNA2 mRNAs showed changes in the murine lupus-like models." (PMID 29349090, 2017). "Besides FOS, FOXO1, and FOXO3, upregulated TBK1 and TNFSF10 contributed to the activation prediction of ‘Systemic Lupus Erythematosus In B Cell Signaling’." (PMID 35406685, 2022). "As increasing evidence links the PRR/TBK1/IRF3 axis to autoimmune disease (including systemic lupus erythematosus [SLE]), vaccine responses, and the development of malignancy, the identification of regulators of this pathway may reveal novel therapeutic targets." (PMID 31346090, 2019). "For instance, TBK1 is not required for IFN-I production in the TLR7-dependent pristane-induced lupus model." (PMID 29559975, 2018). "Below we will discuss the research advances of STING/TBK1/IRF3 isoforms in viral infections, systemic lupus erythematosus (SLE), and cancer." (PMID 34868032, 2021).
herpes simplex encephalitis (13 papers, 2017 to 2025). Herpes simplex virus encephalitis (HSE) is caused by the infection of the central nervous system by Herpes simplex virus (HSV) that could have a devastating clinical course and a potentially fatal outcome particularly with delay or lack of treatment. "Autosomal dominant (AD) and recessive (AR) TBK1 deficiencies have been reported in human patients with herpes simplex encephalitis and SARS-CoV-2 pneumonia (AD deficiency) or systemic inflammation (AR deficiency)." (PMID 41608123, 2025). "Accordingly, mutations present in genes of the TLR3 signaling pathway, such as the gene encoding for TANK-binding kinase 1 (TBK1), correlated with the development of herpes simplex encephalitis (HSE) in children and young adults." (PMID 31114761, 2019). "Human autosomal dominant (AD) TBK1 deficiency was first reported in 2012, in two children with herpes simplex encephalitis (HSE)." (PMID 41608123, 2025). "Moreover, deletion of Mid1 decreased susceptibility of mice to viral myocarditis, pneumonia, and herpes simplex encephalitis by enhancing the production of type I IFN through its interaction with protein phosphatase 1A (PPM1A) responsible for dephosphorylation of TANK binding kinase 1 (TBK1)." (PMID 40443734, 2025). "Gene mutations in nucleic acid sensing components such as TLR3 or its downstream signaling molecules (including UNC93B1, TLR3, TRIF, TRAF3, TBK1, IRF3, etc.)are one of the causes of herpes simplex encephalitis." (PMID 38814453, 2024). "Additionally, some fatal cases of herpes simplex encephalitis (HSE) are associated with defects in key genes in the interferon signaling pathway, such as TRIF, TBK-1, TLR3, and TRAF3." (PMID 40285022, 2025). "Variants in TLR3 as well as TRIF, TRAF3, TBK1, IRF3, and NEMO that code for mediators downstream of TLR3, and UNC93B1 that is involved in TLR3 trafficking, all reduce type I interferon signaling and are reported genetic causes of herpes simplex encephalitis (HSE)." (PMID 35126383, 2021).
cardiac hypertrophy (12 papers, 2016 to 2024). "SIKE1 was reported to have protective roles in induced cardiac hypertrophy by repressing TBK1-AKT-mTOR cascade." (PMID 39417621, 2024). "The TBK1 inhibitor Amlexanox significantly alleviates pressure overload induced-cardiac hypertrophy and myocardial fibrosis in mice with USP38 overexpression." (PMID 38481817, 2024). "In the heart, TRAF3 mediates GPCR (G-coupled protein receptor)-stimulated cardiac hypertrophy through activation of TBK1-AKT-mTOR signaling, which results in increased protein synthesis that contributes to the hypertrophic response." (PMID 34440839, 2021). "The overexpression of SIKE (suppressor of IKKε) attenuated cardiac hypertrophy by regulating the TBK1-AKT signaling pathway." (PMID 34540911, 2021). "In this study, for the first time, to the best of our knowledge, we identified TANK as a scaffold protein activate AKT signaling in pathological cardiac hypertrophy, and provide future evidence for the IKKε-TBK1/AKT signaling pathway." (PMID 34540911, 2021). "The essential function of TBK1 in the suppressive effect of SIKE on cardiac hypertrophy was verified by ‘rescue' experiments using Sike/Tbk1-DKO or DTG mice." (PMID 27249321, 2016). "In summary, this study identifies SIKE as a critical negative regulator of pathological cardiac hypertrophy in rodents and primates, via its direct inhibition of the TBK1/AKT signalling axis." (PMID 27249321, 2016). "Another potential mechanism to treat cardiac hypertrophy, remodeling and heart failure is inhibition of the TBK1/AKT pathway." (PMID 27690014, 2016). "The requirement of the SIKE-TBK1 interaction for SIKE-regulated cardiac hypertrophy was confirmed by the negligible influence of SIKE on cardiac remodelling when SIKE lost its binding capacity to TBK1." (PMID 27249321, 2016). "Herein, we found that USP38 positively regulates pathological cardiac hypertrophy and remodeling by preventing the proteasomal degradation of p-TBK1, leading to the activation of Akt-GSK3β/mTOR signaling pathway and the acceleration of heart failure progression." (PMID 38481817, 2024). "AS-IV has been demonstrated to improve cardiac function and decrease myocardial hypertrophy in several in vivo studies by decreasing oxidative stress and activating calpain-1, inhibiting the TBK1/PI3K/AKT signaling pathway, and several other additional mechanisms." (PMID 35859295, 2022). "Another study indicated that ASIV might be a potential candidate for inhibiting apoptosis and inflammation, thereby preventing cardiac hypertrophy via elevating the suppressor of IKKε (SIKE) to suppress TBK1/PI3K/AKT activity." (PMID 31285785, 2019). "In addition, knockdown of TBK1 almost prevented the cardiac hypertrophy by TRAF3 overexpression in response to Ang II." (PMID 30186311, 2018). "In addition, our mechanistic investigations emphasize the role of TBK1-AKT cascades during SIKE-regulated cardiac hypertrophy." (PMID 27249321, 2016). "Thus, we could conclude that the SIKE-regulated amelioration of cardiac hypertrophy was dependent on its inhibition of TBK1 activation." (PMID 27249321, 2016). "The SIKE–TBK1 interaction and the subsequent restriction of TBK1-AKT signalling demonstrate the cardioprotective role of SIKE in the development of cardiac hypertrophy." (PMID 27249321, 2016). "Here the authors discover one such pathway and show that SIKE, an inhibitor of interferon signalling, prevents pathological but not physiological cardiac hypertrophy by interacting with TBK1 and modulating the TBK1/AKT signalling in rodents and monkeys." (PMID 27249321, 2016). "Collectively, these findings identify SIKE as a negative regulator of cardiac remodelling in multiple animal species due to its inhibitory regulation of the TBK1/AKT axis, suggesting that SIKE may represent a therapeutic target for the treatment of cardiac hypertrophy and heart failure." (PMID 27249321, 2016).
cardiac hypertrophy (continued). "Due to its inhibitory regulation of the TBK1/AKT axis, SIKE has been proposed as a negative regulator of cardiac remodeling in multiple animal species, and may represent a therapeutic target for the treatment of cardiac hypertrophy and heart failure." (PMID 27690014, 2016). "To evaluate the necessity of TBK1 in SIKE-regulated cardiac hypertrophy, we generated a conditional Tbk1-knockout mouse line and crossed this line with an α-MHC promoter-driven Cre TG strain to obtain a mouse line with cardiac-specific ablation of Tbk1 (Tbk1-CKO)." (PMID 27249321, 2016). "Here, we demonstrate that suppressor of IKKɛ (SIKE), a negative regulator of the interferon pathway, attenuates pathological cardiac hypertrophy in rodents and non-human primates in a TANK-binding kinase 1 (TBK1)/AKT-dependent manner." (PMID 27249321, 2016).